KDM4B (lysine demethylase 4B)
Diseases named in the same sentence as KDM4B in open-access papers (continued):
Sharing a sentence is not in itself a finding about the gene and the disease.
breast carcinoma (continued). "Several reports indicate that KDM4 family members are over-expressed in various cancers: KDM4A, KDM4B, and KDM4C are over-expressed in prostate cancer; amplification of KDM4B is shown in medulloblastoma; and KDM4C is required for the growth of breast carcinoma and diffuse large B cell lymphoma." (PMID 36975603, 2023). "For example, semi-selective KDM4 inhibitors that abrogate KDM4B activity have been shown to be efficacious in inhibiting AR-signalling and growth in prostate cancer cells and to be effective in inhibiting the growth of MYC-driven neuroblastomas and breast cancer stem-like cells." (PMID 31390833, 2019). "Targeting KDM4B with the demethylase inhibitors Methylstat or ML-324 activates the Unfolded Protein Response in PTEN-negative Triple-negative Breast Cancer (TNBC), an aggressive and hormone-independent form of breast cancer, sensitizing these cells to PI3-Kinase inhibitors." (PMID 30759871, 2019). "Downregulation of two other KDM4 family members, KDM4A or KDM4B, did not affect the growth of the cell line tested, confirming the specific requirement for KDM4C in basal breast cancer." (PMID 40457074, 2025). "We thus tested the KDM/Jumonji inhibitor JIB-04 across a panel of breast cancer lines and found that the line most sensitive to JIB-04 was HCC1419, which is derived from a nonTN grade 2 tumor and expresses high levels of KDM4B." (PMID 27863398, 2016).
prostate carcinoma (21 papers, 2015 to 2025). A carcinoma that arises from epithelial cells of the prostate gland. "KDM4B overexpression occurs in prostate cancer cells and is associated with their proliferation." (PMID 35317831, 2022). "Histone demethylases are mostly associated with stable genes such as genes involved in DNA repair, DNA recombination and chromosome organization, while the broad inhibitory nature of inhibitors and the low enzymes levels render prostate cancer sensitive to the loss of KDM4B." (PMID 35186950, 2021). "Due to the signaling role of AR in prostate cancer progression, KDM4B should have a critical role in this malignant tumor." (PMID 35317831, 2022). "A number of studies have shown that KDM4B is often overexpressed in breast, colorectal, ovarian, lung, gastric and prostate cancer cells, resulting in H3K9me3 demethylation, subsequent gene expression changes and genomic instability to induce tumors." (PMID 36612032, 2022). "We next characterized the expression of KDM4B and c-Myc in consecutive sections of paraffin-embedded prostatic cancer specimens from a tissue microarray (n = 93) by immunohistochemistry." (PMID 34335964, 2021). "Our results thus provide proof-of-concept evidence that KDM4B inhibitor can be beneficially used to target both AR and c-Myc driven prostate cancers." (PMID 34335964, 2021). "In LNCaP cell lines, NSC636819 inhibits the histone demethylation of KDM4A and KDM4B as well as upregulates the H3K9me3 level, ultimately inhibiting the proliferation of prostate cancer cells." (PMID 35186950, 2021). "Knockout of KDM4B in advanced prostate cancer cells inhibits the expression of the c-MYC gene, leading to improved treatment with enzalutamide." (PMID 35186950, 2021). "Accordingly, KDM4B is an ideal candidate target for advanced prostate cancer given its dual function to coactive c-Myc and AR." (PMID 34335964, 2021). "KDM4B is involved in resisting androgen deprivation and promoting the development of prostate cancer into castration-resistant prostate cancer." (PMID 35186950, 2021). "In castration-resistant prostate cancer cells, KDM4B activated autophagy by regulating the Wnt/β-catenin signaling, and autophagy inhibition attenuated KDM4B-induced cell proliferation." (PMID 35186950, 2021). "Compared to normal prostate tissue, the KDM4B protein level in prostate cancer tissue is significantly downregulated." (PMID 35186950, 2021). "After knockout of KDM4B, the rapid decrease in AR-V7 content inhibits the growth of prostate cancer cells and enhances the efficacy of enzalutamide." (PMID 35186950, 2021). "Targeting KDM4B is thus an alternative therapeutic strategy for advanced prostate cancers driven by c-Myc and AR." (PMID 34335964, 2021). "In prostate cancer cells, KDM4B expression, which correlates with the severity of tumor types, can cooperate with AR to induce the AR response." (PMID 30759871, 2019). "KDM4B expression is also directly induced by androgens via the androgen receptor to promote a more aggressive prostate cancer phenotype." (PMID 30759871, 2019). "At the same time, KDM4B was the first identified androgen receptor AR)-regulated demethylase with effects on AR signaling and turnover and might be a therapeutic target for prostate cancer." (PMID 36755810, 2023). "Previously, it was shown that KDM4B interaction with AR signaling occurs in prostate cancer." (PMID 35317831, 2022). "Findings from this study suggest that the inhibitor specifically targets KDM4B in late S-phase due to activation of PLK1 transcription via B-MYB, justifying the development of this KDM4B inhibitor for AR+ prostate cancer and opening up the possibility for new treatments in the AR+ subgroup of BC." (PMID 34778065, 2021). "The control of KDM4B expression in prostate cancer tissue is abnormal." (PMID 35186950, 2021). "However, the viability of prostate cancer cells significantly decreases after KDM4B was blocked by drugs or gene knockout." (PMID 35186950, 2021).
prostate carcinoma (continued). "In addition to cooperating with AR to promote androgen-dependent gene expression and tumor progression, KDM4B promotes prostate cancer development through an AR-independent mechanism." (PMID 30759871, 2019). "Therefore, HIF-1α plays an important role in modulating anti-androgen responses via KDM4B in prostate cancer." (PMID 29342868, 2018). "In addition, autophagy activation occurs by KDM4B overexpression in prostate cancer cells." (PMID 35317831, 2022). "In addition, KDM4B is not only required for enhancing androgen receptor (AR) transcriptional activity through histone modification, but it also enhances AR protein stability via inhibition of AR ubiquitination, demonstrating the functional connection between AR and KDM4B in prostate cancer." (PMID 29342868, 2018). "Finally, KDM4B, which itself is regulated by androgens, can stimulate AR-mediated transcription not only via demethylation activity but also via modulation of ubiquitination in prostate cancer cells." (PMID 26397136, 2015). "In our analysis, twelve histone demethylases showed gene upregulation in prostate cancers, of which six (KDM1A, KDM4B, KDM5B, KDM5C, KDM7A, and PHF8) were in line with previous reports." (PMID 36776320, 2023). "ML324 is a different KDM4 inhibitor in the arsenal; it specifically targeted KDM4B and KDM4E, suppressed prostate cancer proliferation both in vitro and in vivo, and decreased tumor volume and growth in a triple-negative breast cancer mice model." (PMID 37218871, 2023). "Of note is the case of JMJD2B (KDM4B), which is an AR coactivator, emerging as a suitable therapeutic target for the treatment of prostate cancer." (PMID 29888169, 2018). "For example, KDM4B promotes prostate cancer carcinogenesis via the alteration of AR signaling, and the AR-KDM4A complex promotes prostate cancer progression." (PMID 26397136, 2015). "Furthermore, it prevented KDM4B from binding to the polo-like kinase-1 (PLK1) promoter, showing a possible mechanistic treatment approach to prostate cancer and tumors expressing high levels of KDM4B/PLK1." (PMID 37218871, 2023). "Importantly, KDM4B indirectly induces autophagy via triggering nuclear translation of CTNNB1/β-catenin, leading to prostate cancer progression." (PMID 35317831, 2022).
colorectal cancer (20 papers, 2012 to 2025). A primary or metastatic malignant neoplasm that affects the colon or rectum. "Given the striking effect of KDM4B on tumor growth, we then questioned whether there was an association between KDM4B expression and clinical prognosis in patients with colorectal cancer." (PMID 31931846, 2020). "Our findings strongly suggest that KDM4B may be a useful diagnostic biomarker for colorectal cancer." (PMID 31931846, 2020). "KDM4B promotes the progression of colorectal cancer and glucose metabolism by promoting TRAF6-mediated AKT activation." (PMID 36765702, 2023). "The interaction of Lysine Demethylase 4B (KDM4B) with Akt stimulates the TRAF6-mediated K63-linked ubiquitination and activation of Akt, facilitating glucose metabolism and colorectal cancer growth." (PMID 36769122, 2023). "KDM4B overexpression also promoted proliferation, growth and glucose uptake in colorectal cancer cells whereas KDM4B knockdown inhibited tumor growth significantly in an in vivo model." (PMID 34220955, 2021). "KDM4B promotes the development of colorectal cancer through controlling cell-cycle progression and apoptosis." (PMID 33909202, 2021). "In colorectal cancer cells, the KDM4B protein was found to interact with TCF4, β-catenin and ERG1 (sequence-specific transcription factor ETs-related gene 1), thereby promoting downstream expression of Jun, MYC, Cyclin D1, and TCL (the small GTPase TC10-like)." (PMID 35186950, 2021). "In multiple reports, KDM4B has been found to be overexpressed in colorectal cancer cells and tissues, which is associated with worse prognosis of colorectal cancer patients." (PMID 35186950, 2021). "Knockdown of KDM4B in colorectal cancer cells results in cell cycle arrest at the G2-M phase transition with induction of apoptosis and senescence." (PMID 35186950, 2021). "Expression levels of KDM4B are notably upregulated in numerous cancers, including breast, prostate, bladder, ovarian, gastric and colorectal cancer." (PMID 31931846, 2020). "Here, we sought to delineate the role and mechanism of KDM4B in glucose metabolism in colorectal cancer (CRC)." (PMID 31931846, 2020). "More importantly, higher KDM4B expression in primary tumors is significantly correlated with unfavorable tumor stages and shorter survival in patients with colorectal cancer." (PMID 31931846, 2020). "The oncogenic activities of KDM4B have been extensively investigated in multiple cancers, including breast, prostate, bladder, ovarian, gastric and colorectal cancer." (PMID 31931846, 2020). "When induced by PRL-3 a gene linked to CRC metastasis, KDM4B can promote CRC tumorigenesis by promoting proliferation, colony formation and migration of human colorectal cancer cells." (PMID 30759871, 2019). "Similar to colorectal cancer, KDM4B functions in a complex with β-catenin to increase expression of genes involved in the epithelial-mesenchymal transition in a demethylase-dependent manner." (PMID 30759871, 2019). "In this study, we demonstrate that KDM4B is overexpressed in colorectal cancer and is significant for the mediation of mitochondrial apoptosis in colorectal cells." (PMID 27506941, 2016). "To address the role of KDM4B in colorectal cancer tumorigenesis in vivo, we generated stably KDM4B-depleted cell lines by transducing LoVo cells with KDM4B shRNA lentivirus." (PMID 27506941, 2016). "Hypoxia regulates chromatin modifiers, such as histone lysine-specific demethylase 2B (JMJD2B or KDM4B), whose expressions correlate with the advance of colorectal cancers." (PMID 26861406, 2016). "HAX1 expression was notably downregulated following KMD4B knockdown, and were also increased following KDM4B overexpression in colorectal cancer cell lines." (PMID 27506941, 2016). "Induction of histone lysine-specific demethylase 4B (KDM4B, JMJD2B) correlates with invasion and advanced clinical stage in colorectal cancers." (PMID 23241400, 2012).
colorectal cancer (continued). "Furthermore, KDM4B overexpression has been observed in gastric, bladder, lung, and colorectal cancers, where it is essential for the proliferation, colony formation, invasion, and survival of cancer cells." (PMID 39620228, 2024). "Previous reports suggest that KDM4B silencing inhibits the activity of STAT3 signaling in colorectal cancer, and thus, we tried to detect whether KDM4B can regulate the activity of STAT3 signaling in RA FLS." (PMID 33909202, 2021). "Moreover, loss of KDM4B inhibits the activity of STAT3 to suppress the progression of colorectal cancer, and KDM4B regulates the differentiation of vascular smooth muscle cells into osteoblast-like cells through interacting with STAT3." (PMID 33909202, 2021). "There findings therefore underpin an oncogenic role for KDM4B in colorectal cancer." (PMID 31931846, 2020). "In this study, we found that KDM4B is frequently upregulated in colorectal cancer." (PMID 31931846, 2020). "The reason why KDM4B is overexpressed in colorectal cancer remains to be explored." (PMID 31931846, 2020). "KDM4B is highly expressed and is a known contributor to colorectal cancer (CRC)." (PMID 30759871, 2019). "In this study, we demonstrate that KDM4B is overexpressed in colorectal cancer (CRC) tissues." (PMID 27506941, 2016). "To confirm this hypothesis, we further analyzed HAX1 expression in cells following KDM4B knockdown or overexpression in additional colorectal cancer cell lines." (PMID 27506941, 2016). "In colorectal cancer cells, KDM4B expression is induced by HIF-1α, and KDM4B upregulates the expression of hypoxia-inducing genes such as carbonic anhydrase 9 (CA9) by decreasing H3K9me3 markers in the promoter." (PMID 35186950, 2021). "KDM4B can also directly activate the expression of the HAX1 gene and promote mitochondrial apoptosis in colorectal cancer cells." (PMID 35186950, 2021). "In colorectal cancer cells, the transcription factor CREB directly binds to the appropriate region of the KDM4B promoter to activate KDM4B expression and induces radiation therapy resistance." (PMID 35186950, 2021). "The Lysine Demethylase 4B (KDM4B) could interact with TRAF6 and promote ubiquitination of AKT for activation, thereby promoting glucose metabolism in colorectal cancer cell." (PMID 38264327, 2023). "In colorectal cancer tumor masses, cells become hypoxic because of clumping, and production of the hypoxia inducible factor alpha (HIF-1α) is induced, which directly activates KDM4B transcription and translation." (PMID 35186950, 2021). "In summary, our study demonstrates that KDM4B facilitates colorectal cancer growth and glucose metabolism by stimulating TRAF6-mediated AKT activation, implicating that KDM4B is a potential molecular target for colorectal cancer treatment." (PMID 31931846, 2020). "Taken together, these results show that KDM4B levels are significantly higher in colorectal cancer tissues than in corresponding non-neoplastic tissues." (PMID 27506941, 2016).
gastric cancer (19 papers, 2014 to 2023). A primary or metastatic malignant neoplasm involving the stomach. "Loss of KDM4B in gastric cancer cells, not only inhibits cell proliferation and induces apoptosis, but also inhibits metastasis in vivo." (PMID 35186950, 2021). "Immunohistochemistry analysis of gastric cancer biopsy specimens revealed that elevated KDM4B expression was significantly associated with the abundance of p-c-Jun in cancerous tissues." (PMID 30683841, 2019). "Elevated KDM4B expression is significantly associated with the abundance of p-c-Jun in gastric cancer and is linked to a poor clinical outcome." (PMID 30683841, 2019). "KDM4B can induce Helicobacter pylori infection and resulting gastric inflammation, one of the strongest risk factors for gastric cancer development." (PMID 30759871, 2019). "Another mechanism is that KDM4B upregulates miR-125b expression and activates the Wnt signaling pathway, which promotes gastric cancer metastasis." (PMID 35186950, 2021). "In gastric cancer, metastasis is common and frequent, and KDM4B can promote the epithelial-mesenchymal transformation of cancer cells by physically binding to β-catenin." (PMID 35186950, 2021). "KDM4B overexpression can promote the epithelial–mesenchymal transition and induce gastric cancer metastasis and proliferation." (PMID 33909202, 2021). "In gastric cancer cells, KDM4B binds to the promoter CCNA1 to result in CCNA1 upregulation under hypoxic conditions, thereby promoting cancer cell proliferation." (PMID 35186950, 2021). "The oncogenic roles of KDM4B have been widely probed in different cancers, including ovarian cancer, gastric cancer, as well as CRC." (PMID 33732698, 2021). "Targeting KDM4B, a coactivator of c-Jun and NF-κB, is a potential new strategy for effective therapeutic intervention in gastric cancer progression." (PMID 30683841, 2019). "Increased expression of KDM4B has been shown to drive gastric cancer proliferation, promote epithelial-mesenchymal transitions, and induce COX-2 dependent inflammation." (PMID 30759871, 2019). "KDM4B is connected to gastric cancer carcinogenesis, lending itself as a possible novel biomarker or target for inhibition." (PMID 30759871, 2019). "KDM4B-dependent expression of miR-125b was recently shown to induce b-catenin nuclear translocation and promote gastric cancer metastasis." (PMID 30759871, 2019). "KDM4B was also regulated by hypoxia and radiation to promote the proliferation in gastric cancer cell." (PMID 29651880, 2018). "Similarly, histone demethylase KDM4B/JMJD2B is overexpressed in gastric cancer and is a requisite for tumor cell proliferation." (PMID 37218871, 2023). "In addition, KDM4B has been identified as a gene required for the proliferation and growth of gastric cancer cells, and as a key gene required for Helicobacter pylori-induced gastric carcinogenesis." (PMID 35186950, 2021). "The expression of the KDM4B is increased in human primary gastric cancer tissues." (PMID 35186950, 2021). "Taken together, our results suggest that KDM4B recruits c-Jun and promotes IL-8 production via JNK/c-Jun signaling, possibly involving a positive feed-forward loop under stress-associated conditions in gastric cancer." (PMID 30683841, 2019). "Thus, our results reveal a novel function of KDM4B in controlling the JNK/c-Jun-induced IL-8-IL-8R axis in gastric cancer, and offer a new strategy in cancer therapy." (PMID 30683841, 2019). "Furthermore, KDM4A and KDM4B are often amplified in gastric cancer, neuroblastoma, and ovarian cancer." (PMID 30683841, 2019). "To test whether KDM4B serves as a general regulator of IL-8 production for gastric cancer cells infected with H. pylori, we compared the production of IL-8 in various gastric cancer lines including AGS, MKN28, MKN45, and SNU601." (PMID 30683841, 2019).